REN (renin)
Diseases named in the same sentence as REN in open-access papers (continued):
Sharing a sentence is not in itself a finding about the gene and the disease.
periodontitis (9 papers, 2015 to 2025). An acute or chronic inflammatory process that affects the tissues that surround and support the teeth. "Regarding the local renin–angiotensin system in gingival tissue, there may be another pathogenic link between the two conditions under investigation, in addition to a possible variable risk of periodontitis among different renin–angiotensin system genetic polymorphisms." (PMID 37711554, 2023). "The renin-angiotensin system is thought to be involved in inflammatory processes such as periodontitis." (PMID 37983238, 2023). "In this study, we evaluated the influence of the renin-angiotensin system on ligature-induced periodontitis, more specifically, the interaction between angiotensin II and its receptors, as several studies have reported the participation of this system in the pathogenesis of inflammatory disorders." (PMID 34884653, 2021). "The initiation or progression of periodontitis might involve a local renin-angiotensin system (RAS) in periodontal tissue." (PMID 26244896, 2015). "Notably, the renin-inhibitor aliskiren and AT1R-inhibitor losartan were able to prevent bone loss in rats when treated daily for 14d after induction of experimental periodontitis (EP)." (PMID 26244896, 2015). "A longitudinal, database case-control study concluded that patients with periodontitis purchased more than 19 different subgroups of medications compared with healthy periodontal individuals, including calcium channel blockers, agents acting on the renin-angiotensin system, and statins." (PMID 39157205, 2024).
pheochromocytoma (9 papers, 2010 to 2025). "Once rare causes have been eliminated (such as pheochromocytoma, licorice, adult coarctation of the aorta), the cause will usually be found by intelligent interpretation (in the light of medications then being taken) of plasma renin and aldosterone." (PMID 21532778, 2010). "Furthermore, patients with pheochromocytoma should be considered to be volume depleted because of a chronically elevated adrenergic state, which may lead to an inhibition of renin-angiotensin activity, resulting in excessive fluid loss." (PMID 22222147, 2012). "Plasma renin activity (PRA) is generally increased in patients with pheochromocytoma (PCC) due to low circulating plasma volume and activation of β-1 adrenergic receptor signaling." (PMID 32917197, 2020). "The elevated plasma renin activity was postulated to be due to ectopic renin secretion from the tumor, although pheochromocytoma remained highest on the differential." (PMID 26997629, 2016). "Our patient refused surgical resection of pheochromocytoma, so we administered an α-blocker, β-blocker, and ARNI to inhibit the renin-angiotensin-aldosterone system and improve the patient’s symptoms." (PMID 36401171, 2022).
pneumonia (9 papers, 2015 to 2023). An acute, acute and chronic, or chronic inflammation focally or diffusely affecting the lung parenchyma, caused by an infection in one or both of the lungs (by bacteria, viruses, fungi, or mycoplasma.). "The release of the cytokine storm in patients with severe pneumonia is related to the over-expression of toxic angiotensin II in the renin-angiotensin system (RAS)." (PMID 37176159, 2023). "After virus entry into cells, membrane ACE2 is downregulated, leading to an imbalance in the renin–angiotensin pathway, thereby promoting angiotensin II-induced vascular permeability and pneumonia with vascular injury." (PMID 33668613, 2021). "Animal studies have demonstrated that renin-angiotensin-aldosterone inhibitors were able to effectively relieve symptoms of severe pneumonia." (PMID 32624690, 2020). "Additionally, increased renin-angiotensin-aldosterone system activity is a poor prognostic factor for severe pneumonia." (PMID 32624690, 2020). "Recent evidence shows that vitamin D is a negative endocrine modulator of the renin–angiotensin system (RAS), with protection from diseases leading to lung damage, such as pneumonia caused by various pathogens." (PMID 36358201, 2022). "Based on KEGG enrichment analysis, the renin–angiotensin system was a significantly enriched pathway in patients with KD that was not enriched in patients with pneumonia." (PMID 30761252, 2019). "As an enriched protein of the renin–angiotensin system, MME (neprilysin) was down‐regulated in patients with KD while not differentially expressed in patients with pneumonia compared to normal control." (PMID 30761252, 2019).
thrombosis (9 papers, 2015 to 2025). "Current data suggest that renin–angiotensin–aldosterone system (RAAS) blockers can reduce the risk of thrombosis at least partly independently of blood pressure control." (PMID 34876633, 2021). "Moreover, the activation of the renin-angiotensin system is associated with increased angiotensin-II concentration with subsequent activation of the inflammatory cytokines "cytokine storm" in the vascular endothelium, vasculopathy, and thrombosis." (PMID 38313184, 2023). "The pathogenesis of this prothrombotic state is mediated by several mechanisms, including direct viral invasion of endothelial cells, immune-mediated thrombosis and hypercoagulopathy, and activation of the alternative renin-angiotensin system pathway." (PMID 38667532, 2024). "The renin-angiotensin system plays a critical role in the hypercoagulation status and thrombosis development." (PMID 38313184, 2023).
acute myeloid leukemia (8 papers, 2016 to 2023). Acute myeloid leukemia (AML) is a group of neoplasms arising from precursor cells committed to the myeloid cell-line differentiation. "The KEGG pathways involved those designated for complement and coagulation cascades, the renin–angiotensin system, neuroactive ligand–receptor interaction, acute myeloid leukemia, the Fc epsilon RI signaling pathway, and others." (PMID 37091784, 2023). "Renin is expressed on cells from acute myeloid leukemia, chronic myeloid leukemia, and acute lymphocytic leukemia and its expression disappears following acute myeloid leukemia remission." (PMID 35574555, 2022). "At the same time, some molecular subtypes of tumors cannot be explained by standard clinical parameters or commonly used biomarkers; the emergence of the renin–angiotensin system genes as a new prognostic marker of acute myeloid leukemia (AML) may solve this problem." (PMID 35359375, 2022).
Alkalosis (8 papers, 2006 to 2025). Depletion of acid or accumulation base in the body fluids. "The defect in NCCT gene leads to NaCl wasting which stimulates the renin-angiotensin-aldosterone system, resulting in hypokalemic metabolic alkalosis." (PMID 16723030, 2006).
amyotrophic lateral sclerosis (8 papers, 2019 to 2025). Amyotrophic lateral sclerosis (ALS) is a neurodegenerative disease characterized by progressive muscular paralysis reflecting degeneration of motor neurons in the primary motor cortex, corticospinal tracts, brainstem and spinal cord. "Adrenergic signaling in cardiomyocytes, amyotrophic lateral sclerosis, the renin–angiotensin system and the GnRH signaling pathway were enriched in the KEGG pathway." (PMID 38254476, 2024). "Based on the differential abundance scores, “amyotrophic lateral sclerosis”, “pyruvate metabolism”, “citrate cycle (TCA cycle)”, “renin-angiotensin system”, and “thyroid hormone synthesis” were the top five pathways." (PMID 40870583, 2025).
angioedema (8 papers, 2017 to 2025). Swelling involving the deep dermis, subcutaneous, or submucosal tissues, representing localized edema. "Extensive clinical evaluations of commonly used inhibitors of the renin-angiotensin system provide reliable data on the incidence and clinical manifestations of angioedema caused by these drugs." (PMID 39081961, 2024). "For aliskiren (renin inhibitor) lower and equal angioedema incidences are reported compared to ACEi." (PMID 32214375, 2020). "Angioedema is a known adverse drug reaction (ADR) for drugs acting on the renin-angiotensin system (RAS) with varying incidences for the individual drug classes." (PMID 32214375, 2020). "Kinin-mediated angioedema associated with angiotensin converting enzyme inhibitors and direct renin inhibitors presents without urticaria." (PMID 28616043, 2017). "However, the use of aliskiren, a direct renin inhibitor (DRI), was associated with an increased hazard rate ratio for AE of 2.85 (95% CI: 1.34–6.04), but only seven patients on aliskiren developed angioedema." (PMID 29728119, 2018).
Hypercalcemia (8 papers, 2011 to 2025). An abnormally increased calcium concentration in the blood. "Blood magnesium was normal, however, severe hypercalcemia (11 mg/dl) was found and plasma renin and aldosterone levels were increased: renin 4600 ng/ml (ref. range 0.84–2.5) and aldosterone 3903 pg/mL (ref. range 5.7–240), respectively." (PMID 36645652, 2023). "Suggested mediators have included hypercalcemia, high PTH, plasma renin, renal functions, uric acid, and BMI." (PMID 21403888, 2011).
hyperphosphatemia (8 papers, 2014 to 2025). Abnormally high level of phosphate in the blood. "AS was associated with mechanisms such as AGE accumulation, vascular calcification, and activation of the renin–angiotensin–aldosterone system, while hyperphosphatemia further contributed to vascular injury through inflammatory and oxidative pathways." (PMID 40806693, 2025). "Klotho deficiency is associated with reduced renal function, hyperphosphatemia, increased FGF23 levels, renin–angiotensin–aldosterone system (RAAS) activation, inflammation, and chronic complications such as ectopic calcification, among others." (PMID 35887617, 2022). "When hyperphosphatemia occurred in the HD patients, the serum FGF-23 level elevated, 1,25(OH)2D3 level decreased, and renin-angiotensin-aldosterone system activation, all may deteriorate the systemic inflammation." (PMID 24558316, 2014).
hypertensive nephropathy (8 papers, 2015 to 2025). Kidney damage that results from chronically elevated blood pressure; complications include glomerular damage resulting in proteinuria and hematuria. "The main pathogenesis of hypertensive nephropathy is related to hemodynamic changes, oxidative stress, inflammatory response, excessive activation of the renin-angiotensin system, and genetic and metabolic factors." (PMID 35617324, 2022). "Ang II is the main effective peptide in the renin-angiotensin system and is considered to be a key mediator in the development of hypertensive nephropathy." (PMID 26170892, 2015). "Ang II is the main effective peptide in the renin-angiotensin system and is considered to be a key mediator in the development of hypertensive nephropathy, Rüster and Wolf (2011)." (PMID 26170892, 2015). "The treatment of primary hypertension—blood pressure control—is an important component of the treatment of patients with hypertensive nephropathy, and the use of renin-angiotensin-aldosterone system blockers in combination with calcium channel blockers or diuretics is recommended." (PMID 35617324, 2022). "Although antihypertensive treatments with ACE inhibitors, such as angiotensin receptor blockers, renin inhibitors, and aldosterone antagonists, could reduce the severity of hypertensive kidney disease, they are not enough to prevent the progression of hypertensive nephropathy." (PMID 33921823, 2021).
Hypoglycemia (8 papers, 2013 to 2025). A decreased concentration of glucose in the blood. "In hypoglycemia, the activation of the renin-angiotensin system caused an increase in plasma aldosterone which in turn increased renal potassium excretion." (PMID 30105256, 2018). "Spr−/− mice exhibited hypoglycemia and elevation of plasma renin activity." (PMID 28320892, 2017).
kidney injury (8 papers, 2020 to 2025). Trauma to the kidney. "Thus, there is a tight dependency between renin release and reduced blood flow to the post-glomerular capillaries, which can lead to ischemic kidney injury." (PMID 38420620, 2024). "Additionally, there is an increase in blood renin and angiotensin levels of patients with kidney injury." (PMID 36297415, 2022). "In addition, severe dehydration might contribute to acute kidney injury, because marked increase in serum renin was definite at this admission." (PMID 34021486, 2021).
polycystic ovary syndrome (8 papers, 2017 to 2024). A disorder that manifests as multiple cysts on the ovaries. "An abnormal ovarian renin–angiotensin system has been associated with ovarian pathologies such as polycystic ovarian syndrome, ovarian hyperstimulation syndrome, and ovarian cancer." (PMID 35955748, 2022). "Polycystic ovary syndrome (PCOS) is one of the most common endocrine disorders which is associated with increased activity of the renin-angiotensin system (RAS) and hyperandrogenism in women." (PMID 28042549, 2017). "Renin plays a significant role in the metabolic abnormalities observed in polycystic ovary syndrome (PCOS), particularly in relation to IR, as women with PCOS exhibit higher renin levels that positively correlate with insulin concentrations and HOMA-IR." (PMID 39858399, 2024). "We assume that in a pathological condition such as PCOS, numerous hyperandrogenemia-inducing mechanisms (e.g., IR, hypo-SHBG-emia, under-reported roles of systemic and ovarian renin-aldosterone-renin system) simply “overtrump” the impact of diet-related factors." (PMID 35010948, 2021).
psoriasis (8 papers, 2013 to 2025). An autoimmune condition characterized by red, well-delineated plaques with silvery scales that are usually on the extensor surfaces and scalp. "The Polymorphism of interleukin (IL)-23R and IL-23 genes, as well as other genes involved in lipid and fatty-acid metabolism, renin-angiotensin system and endothelial function, have been described in patients with psoriasis and with cardiovascular risk factors." (PMID 40977704, 2025). "In particular, polymorphism in the IL-23R and IL-23 genes, as well as other genes involved in lipid and fatty-acid metabolism, renin–angiotensin system and endothelial function, have been described in patients with psoriasis and with cardiovascular risk factors." (PMID 36012327, 2022). "Psoriasis patients have an alteration of the renin-angiotensin-aldosterone system (RAAS), with elevated plasma renin activity and elevated angiotensin-converting enzyme activity." (PMID 25713604, 2014). "Moreover, patients with psoriasis have an enhanced renin activity and increased urinary aldosterone excretion." (PMID 36012327, 2022). "Case reports are available about psoriasis induction by clonidine, “agents acting on the renin-angiotensin system” like captopril or losartan; the “protein kinase inhibitor” and “antineoplastic agent” imatinib; diclofenac, olanzapine, fluoxetine and chloroquine." (PMID 24303025, 2013).
sleep disorder (8 papers, 2019 to 2025). A change from the patient's baseline sleeping pattern, in the hours slept and/or an alteration/dysfunction in the stages of sleep. "Body dehydration associated with sleep disorders may be due to a decrease in blood pressure during the night, as well as a decrease in the levels of the renin-angiotensin-aldosterone system activity." (PMID 41203229, 2025). "Sleep disorders cause mild activation of the hypothalamic-pituitary-adrenal axis in humans, leading to diuresis and excessive natriuresis; in addition, the circadian rhythm of hormones in the renin-angiotensin-aldosterone system is significantly altered." (PMID 35069294, 2021). "Although antidiuretic hormone levels remain unchanged by sleep disorders, the circadian rhythm of the renin-angiotensin-aldosterone system is significantly altered." (PMID 41203229, 2025). "The results of KEGG analysis showed that the mechanism of action of AMS in treating sleep disorders mainly involves the dopamine synaptic pathway, the neuroactive ligand–receptor interaction, the renin-angiotensin system, the synaptic vesicle cycle pathway, and other signaling pathways." (PMID 38784223, 2024). "It has been suggested that a potential mechanism for dehydration in sleep disorder may involve a reduction in nocturnal blood pressure and a decrease in the renin-angiotensin-aldosterone system hormones." (PMID 35069294, 2021).
uremia (8 papers, 2012 to 2025). A clinical syndrome associated with the retention of renal waste products or uremic toxins in the blood. "Persistent uremia results in thickening of myocardial cells and concentric remodeling of the left ventricle together with activation of the intracardiac renin-angiotensin system, which induces hyperaldosteronemia." (PMID 36967775, 2023). "Different cardiorenal connectors (renin–angiotensin or sympathetic nervous system activation, inflammation, uremia, etc.)and non-traditional risk factors potentially contribute to multi-organ failure." (PMID 29367550, 2017). "The renin-angiotensin system (RAS) activated by hypotension following HD, uremia, or hypovolemia may cause vasospasms that include mesenteric vessels, thereby leading to intestinal necrosis and nonobstructive mesenteric ischemia." (PMID 24391670, 2013). "A higher fluorescence intensity at both 440 nm and 490 nm was observed in CKD patients in comparison with healthy subjects, which could be explained by the stimulated formation and excretion of AGEs due to oxidative stress (e.g., uremia) and activation of the renin-angiotensin system." (PMID 31936498, 2020).
acute coronary syndrome (7 papers, 2012 to 2025). Signs and symptoms related to acute ischemia of the myocardium secondary to coronary artery disease. "The Aliskiren and Valsartan to Reduce NT ProBNP via Renin-Angiotensin-Aldosterone-System Blockade (AVANT GARDE)-TIMI 43 study enrolled 1,101 patients with elevated NT ProBNP (> 400 pg/mL) 3 - 10 days after an acute coronary syndrome (ACS) event." (PMID 28348679, 2012).
arteriosclerosis (7 papers, 2020 to 2024). A vascular disorder characterized by thickening and hardening of the walls of the arteries. "Arterial stiffness and peripheral arteriolar resistance, the main physiological features that increase blood pressure, can be increased by arteriosclerosis, elevated sympathetic activity that increases the tonus of the arterioles, renin-angiotensin system, and increased body fluid volume." (PMID 36573720, 2022). "However, salt restriction also contributed to significant increase in plasma renin, aldosterone, norepinephrine and epinephrine as well as 2.5% increase in cholesterol and 7% increase in TG, all of which are closely related to arteriosclerosis." (PMID 34477293, 2021). "High salt activates renin‐angiotensin‐aldosterone (RAAS) system and sympathetic system and inhibits synthesis of nitric oxide produced by endothelial cells, which are closely associated with arteriosclerosis." (PMID 34477293, 2021).
Autoimmunity (7 papers, 2014 to 2025). The occurrence of an immune reaction against the organism's own cells or tissues. "Different studies in the last year focused on potential mechanism behind autonomic dysfunction of post COVID- 19, identifying neuroinflammation, autoimmunity, and disruption in the renin-angiotensin system or endothelial damages as key contributors." (PMID 40281597, 2025). "Studies have revealed the presence of a local renin–angiotensin system in the skin, where the angiotensin-converting enzyme (ACE) is involved in autoimmunity and causes alopecia due to HF’s chronic inflammation." (PMID 37763773, 2023). "On the other hand, some studies have proposed that the renin-angiotensin-aldosterone system (RAAS) may play a role in autoimmunity." (PMID 25349723, 2014). "However, it is surprising, that the renin–angiotensin–aldosterone system (RAAS) may have a role in organ-specific autoimmunity through the regulation of these cells." (PMID 35563559, 2022).